EGFR (epidermal growth factor receptor)
Diseases named in the same sentence as EGFR in open-access papers (continued):
Sharing a sentence is not in itself a finding about the gene and the disease.
tumor (continued). "First, second and third generation CAR NK cells have been generated, using lentiviral vectors, to target tumor antigens such as CD19, CD20, CD33, CD7, CD22, ErbB2 and EGFR." (PMID 33450862, 2021). "Although osimertinib, as a third-generation and irreversible TKI, is now the front-line treatment for EGFR mutant NSCLC with superior central nervous system and survival outcomes, tumour relapse is inevitable." (PMID 34572879, 2021). "Another anti-tumor drug ENDOSTAR, inhibits cancer angiogenesis through targeting vascular EGFR, has been used in clinical tumor treatment." (PMID 34822512, 2021). "Studies using different tumor cell lines, including NSCLC lines, have shown that hypoxia induces the expression of EGFR and its ligands." (PMID 34381712, 2021). "Epidermal Growth Factor Receptor (EGFR) is a tyrosine kinase receptor which plays a crucial role in many carcinogenic processes, including tumor cell proliferation, angiogenesis, invasion and metastasis, inhibition of apoptosis, etc.." (PMID 34356665, 2021). "EGFR status was tested by digital-droplet PCR (ddPCR) and fluorescent in situ hybridisation (FISH) in tumour samples and by ddPCR in plasma samples, and was correlated with progression free (PFS) and overall survival (OS) in the trial population." (PMID 33199443, 2021). "We performed immunoblot studies of tumor digests to detect changes in MET, pMET, EGFR, HER2, and pHER2 on cetuximab or INC280 and trametinib treatments." (PMID 32646879, 2021). "For right-sided tumours a significant PFS and OS benefit was observed for CMS4 tumours when anti-EGFR was added to irinotecan as second line chemotherapy for both PFS (HR 0.17, 95% CI 0.04–0.71, P = 0.02) and OS (HR 0.20, 95% CI 0.05–0.83, P = 0.03)." (PMID 34253874, 2021). "Plasma levels of VEGFR3 and EGFR were significantly decreased after tumor resection (VEGFR3: p = 0.0119, EGFR: p = 0.0058, paired t-test)." (PMID 34298853, 2021). "This process implies a synergy between IL‐25R and EGFR signal transduction, which finally mediates STAT3 activation and tumor development." (PMID 34128588, 2021). "The expression and activities of the epidermal growth factor receptor (EGFR) in epithelium parallel the pattern of HPV oncogene expression in productive HPV infections and early neoplasia." (PMID 33481911, 2021). "First, we analyzed the EGFR-derived circRNA expression in 4 CRC tissues and paired adjacent non-tumor tissues using RT-qPCR." (PMID 34320120, 2021). "Diminished surface EGFR led to reduction of TNBC cell invasion and colony formation in vitro and tumor growth in vivo." (PMID 34207383, 2021). "The treated tumor showed several CNVs in driver genes, including amplifications in MCL1, TERT, CCND1, AKT1, MYC, EGFR, and FGFR3; deletions in CDK1B, CDKN2A and CDKN2B; a PIK3CA hotspot mutation; and a high TMB." (PMID 34680239, 2021). "Currently, the only rational molecular-targeted therapy for LSCC is cetuximab (C225/Eribitux), a monoclonal antibody that inhibits the epidermal growth factor receptor (EGFR), which is expressed on tumor cells." (PMID 34272446, 2021). "STAT3 has also been found to be a Src-dependent mediator of EGFR-stimulated growth of HNSCC in vitro and decreased apoptosis and increased tumour growth in vivo." (PMID 34298667, 2021). "Upon ligand binding to EGFR, the AKT signaling pathway will be activated, leading to enhanced glycolysis and oncogenic phenotypes in tumor cells." (PMID 34627260, 2021). "Treatment with the small-molecule EGFR inhibitor gefitinib suppressed EREG/EGFR downstream signaling pathways and reduced tumor formation in xenograft animals bearing EREG-overexpressing GBM cells." (PMID 34884633, 2021). "José was always at the frontline of research on new molecular targets, and in addition to anti-EGFR and HER2 therapies he became interested in those blocking the PI3K/mTOR pathway, which regulates tumor progression." (PMID 33962670, 2021).
tumor (continued). "In the present study, we found that DCN alters the E-cadherin–EGFR–ERK axis to inhibit invasion and tumor growth of IBC cells." (PMID 33452400, 2021). "Currently, several chemical inhibitors against EGFR were developed, considering the important biological impact of EGF and their receptors in tumor cells." (PMID 34445562, 2021). "For the assessment of EGFR status during TKI therapy, liquid biopsy testing allows for improved estimation of tumor heterogeneity by detecting molecular sub‐types in NSCLC patients." (PMID 33942501, 2021). "Persistent Kirsten Rat Sarcoma (KRAS)-epidermal growth factor receptor (EGFR) pathway activation cooperates with TGFβ signaling to endow PDAC and TNBC tumor cells with chemoresistance, metastatic dissemination, and early recurrence." (PMID 33802809, 2021). "Some tumor cells were positive for CD68, smooth muscle actin, vimentin and epidermal growth factor receptor." (PMID 33731032, 2021). "Through a systems medicine approach, it was determined that hub biomolecules, AR, GATA2, miR-124, TOR1AIP1, ESR1, EGFR, STAT1, miR-192, GATA3, COL1A1, in tumor microenvironment generic network." (PMID 33907495, 2021). "This transient spike in ctDNA was reported previously for KRAS and EGFR in NSCLC, probably reflecting tumor DNA release by death of tumor cells upon initiation of systemic treatment." (PMID 34449963, 2021). "Intriguingly, RAC1 is enclosed into these exosomes and participates in Integrin, EGFR, CCKR, and FGF signaling pathways in the tumor microenvironment." (PMID 34326687, 2021). "The findings of this study pave the way for validating the impact of the combination of DCA with gefitinib or erlotinib on tumor growth in vivo, in addition to investigating the impact of DCA when combined with the second- and third-generation EGFR-TKi." (PMID 34830434, 2021). "Since miR-134 targets and inactivates KRAS, Nanog mRNA, HNF4α, EGFR, ITGB1, and FOXM1, it also inhibits tumor invasion and metastasis." (PMID 33331954, 2021). "For example, ATM is highly expressed in the microvascular proliferative zones of the tumor, EGFR is highly expressed in the cellular bulk of the tumor while MET is enriched in the leading edges and the necrotic tumor regions." (PMID 33765907, 2021). "The mechanism of osimertinib resistance depends on the high tumor heterogeneity of NSCLC, which is divided into EGFR-dependent and EGFR-independent aspects." (PMID 34391435, 2021). "Therefore, it is crucial to highlight that the current approval of osimertinib is restricted to the adjuvant therapy after complete tumor resection in adult patients with stage IB-IIIA non-squamous cell lung carcinoma harboring EGFR exon 19 deletions or exon 21 (L858R) substitution mutations." (PMID 34440926, 2021). "After TKI treatment, the proportion of TKI-sensitive tumor cells with a high expression of EGFR VIII was significantly decreased, whereas cells with low EGFR VIII expression were increased." (PMID 34568472, 2021). "To enhance NK cell anti-tumor reactivity, we knocked-in a CAR that targets epidermal growth factor receptor (αEGFR-CAR) to the TRAC locus." (PMID 34162850, 2021). "One approach was focused on combining KRAS inhibition with epidermal growth factor receptor (EGFR) TKIs, as the EGFR signaling pathway is often activated in tumor cells to bypass KRAS inhibition." (PMID 35096591, 2021). "EGFR was confirmed as the downstream of circ_CELF1/miR-491-5p and involved in NSCLC tumor progression." (PMID 34788230, 2021). "Relative to PLGA-PEG@DOX/anti-EGFR nano-micelles treatment alone, the combination with UMC was better able to suppress tumor growth even at low concentrations." (PMID 34298600, 2021). "The epidermal growth factor receptor (EGFR) is a tyrosine kinase receptor and is overexpressed in many tumor cell types, including CCA." (PMID 33946151, 2021).
tumor (continued). "The inhibition of EGFR protein expression was consistent with a decrease in micro-vessel density (CD31 biomarker), which may have been caused by the decrease in Ki67 protein tumor proliferation and enhanced tumor apoptosis (cleaved caspase-3 protein and TUNEL data)." (PMID 34575510, 2021). "We have shown earlier that CAFs increase resistance to cetuximab treatment (a monoclonal antibody against EGFR; Erbitux®, Merck KGaA) and increase the MMP1 expression of HNSCC cells during co-culturing compared with tumor cells grown alone in a 2D model." (PMID 34283070, 2021). "Emerging data suggest that EGFR mRNA is overexpressed in a variety of human tumors, including NSCLC, and is involved in tumor growth." (PMID 34830377, 2021). "EGFR is frequently overexpressed in NSCLC and triggers the MAPK signaling cascade to induce tumor growth and metastasis." (PMID 34102455, 2021). "Previously, we demonstrated the downregulation of EGFR protein levels in diffusion-limited and mostly CA IX-positive areas of HNSCC tumor specimens." (PMID 33718186, 2021). "This positions the current study as a starting point in refining selection criteria for anti-EGFR therapy based on CMS and primary tumour location." (PMID 34253874, 2021). "In another study, compared with PDX SCID mice with wild-type EGFR, TGR and tumor cell dissemination were significantly increased in PDX SCID mice with mutated versions of EGFR after nivolumab therapy." (PMID 34290608, 2021). "EGFR-dependent pathways activate MEK-ERK and other downstream effectors, thereby driving tumor cell proliferation." (PMID 34070180, 2021). "EGFR is a well investigated RTK whose activation and signaling contribute to tumor initiation and development, including proliferation, invasion, and metastasis." (PMID 34178975, 2021). "Human EGFR (EGFR; HER-1) is over-expressed in 40%–60% of primary GBM tumours and mostly occurs in the classical subtype, but EGFR mutation which leads to EGFRvIII expression present in 20%–30% of primary GBM." (PMID 33680090, 2021). "Generally, an upward trend was observed in the mRNA levels of total EGFR, ErbB2, and ErbB3 from the PDX tumours treated with infigratinib." (PMID 34156519, 2021). "We further verified the inhibitory effect of AZD3759 on the EGFR and JAK/STAT signaling pathways in tumor tissues." (PMID 34635007, 2021). "Long-term survival and expansion of drug-tolerant cells in vitro were inhibited by combining EGFR and FGFR inhibitors and prevented in vivo tumor relapse in xenograft models." (PMID 34071428, 2021). "In line with this, suppression of viability and tumour growth was more consistent when ARS-1620 was combined with GDC0941 (pan-PI3K inhibitor), compared to afatanib (EGFR/ErbB inhibitor), in different ARS-1620 monotherapy-resistant models." (PMID 34200676, 2021). "Further, increased EGFR and HER2 activity was known to promote constant activation of STAT3, which leads to tumor progression and survival." (PMID 34572912, 2021). "EGFR amplifications were more frequent in GBMs than in LGGs, while PDGFRA amplifications were more homogenous among different tumor grades." (PMID 33673104, 2021). "Mg in tumor voxels of patients with MGMT methylation and EGFR amplification was significantly higher than in tumor voxels of patients with MGMT unmethylated tumors and no EGFR amplification with p = 0.02." (PMID 34298788, 2021). "The results also demonstrated that SH-1028 induced profound shrinkage at low doses against both EGFR TKI-sensitizing and T790M + resistant tumor xenograft models." (PMID 33986687, 2021). "NID2 suppresses the EGFR/Akt and integrin/focal adhesion kinase (FAK)/PLC metastasis-related pathways; these data shed light on NID2’s critical tumor metastasis-suppression functions in cancer." (PMID 34976811, 2021).
tumor (continued). "More important, treatment with Afatinib can markedly slow down the proliferation (p < 0.001) and increase apoptotic (p < 0.001), compared with control and sgCALM1-1 group, strongly suggesting the tumor-promoting role of CALM1 and EGFR in ESCC cells." (PMID 33602237, 2021). "By screening neutralizing antibodies against surface proteins and cytokines, we identified an EGFR monoclonal antibody (mAb), clone LA1, as a strong inhibitor of tumor cluster formation of L2G-labeled TN1 PDX cells." (PMID 33995681, 2021). "Another possible new benefit of knowing the absolute ρR of EGFR and HER2, and their CVs, is that this information would permit the calculation of an estimate of the total number of receptors in the patient tumor." (PMID 34831465, 2021). "We further investigated if miR-30c regulates tumor cell cluster formation and if miR-30c has any regulatory effects on CD44 and EGFR levels." (PMID 33995681, 2021). "The next best targets are overexpressed proteins on tumor cells compared to healthy cells, which is the case for most of the clinically targeted TAAs, such as CEA, EGFR, EpCAM and HER2." (PMID 33466732, 2021). "Our analysis implied that tumor cells co-express CXCL1 and EGFR, but expression levels of CXCR2, HB-EGF, and ADAMs are relatively low." (PMID 33941851, 2021). "However, until now, there was not any effective and convenient ways for clinicians to distinguish whether a patient is harboring a high ratio of EGFR mutation in tumor or not." (PMID 34692766, 2021). "The VHL-HIFα–EGFR pathway increases the proliferation and survival of RCC tumor cells through downregulation of RAF–MEK–ERK." (PMID 34575959, 2021). "Another study found that IL-22 exposure increased the expression levels of phosphorylated-AKT, EGFR, and ERK in the tumor microenvironment after gefitinib treatment versus the control group." (PMID 33466795, 2021). "Previous studies have reported that the EGFR and Src-mediated STAT3 signalling pathways can contribute to tumour aggressiveness and treatment resistance." (PMID 34407787, 2021). "Previous reports have suggested that GALNT7 is involved in the regulation of tumor progression through PI3K/Akt/mTOR and EGFR/PI3K/AKT pathways." (PMID 34819077, 2021). "Several authors have extensively demonstrated the expression of GBM markers, such as EGFR, MGMT, IDH1 R132H, and ATRX, in tumor cells using IHC, which is much more applicable for neuropathology routine." (PMID 33673104, 2021). "It has been reported that the tumor progression and invasion are driven by the ECM-dependent mechanosensitization of EGFR signaling." (PMID 34360896, 2021). "The co-stimulatory capacities of αEpCAM–TNFL fusion proteins were first examined with 2D adherent MCF-7 cells with regard to cytotoxicity elicited by the weakly expressed tumor antigens CEA and EGFR." (PMID 34484225, 2021). "We investigated the efficacy of ribociclib, a CDK4/6 inhibitor, in combination with cetuximab, a monoclonal antibody targeting the EGFR, in HPV-negative SCCHN patient-derived tumor xenograft (PDTX) models." (PMID 33809148, 2021). "IL-26 induced dephosphorylation and downmodulation of EphA3 in TNBC, which resulted in increased phosphorylation of AKT and JNK against EGFR-TKI-induced endoplasmic reticulum (ER) stress, leading to tumor growth." (PMID 34021125, 2021). "Pharmacological analysis of the inhibitor of EGF/EGFR, piperlongumine, had been shown to have an anti-tumor effect on HCC, which was achieved through inhibiting angiogenesis via the EGF/EGFR signaling pathway." (PMID 32379058, 2020). "The addition of EGFR, MEK or ERK inhibitors, which totally or partially blocked the phosphorylation of RSK3, exaggerated the responsiveness of tumour cells to JQ1." (PMID 31937753, 2020). "To identify the molecular mechanism by which GEM inhibits tumor growth, we investigated the effects of the GEM implant on EGFR phosphorylation and total protein levels." (PMID 32111094, 2020).
tumor (continued). "The ctDNA analysis was considered to be uninformative for 37% (13/35) of the patients, since neither the T790M resistance mutation nor the original sensitizing EGFR mutation could be detected, and most likely in these cases the tumor is not shedding adequate levels of DNA for detection." (PMID 32714871, 2020). "(c) Vandetanib is another dual EGFR and VEGFR TKI evaluated for its anti-tumor effect both in vitro and in vivo." (PMID 33302367, 2020). "Cetuximab is an antibody that binds to the extracellular domain of EGFR where it inhibits EGFR signaling and cell cycle progression and promotes apoptosis in HNSCC tumor cells." (PMID 33281820, 2020). "Even though we focused mostly on EGFR mutant NSCLC, we have also shown that the MLD strategy can potentially be effective in other tumour types." (PMID 32572029, 2020). "We observed a decreasing expression level of HSPB8 and PRKN and an increasing expression level of EGFR, CDKN2A, FADD, and ITGA3 in tumor samples." (PMID 33456497, 2020). "However, the EGFR T790M mutation, acquired RTK MET gene amplification and PIK3CA mutations, share the same effect of reestablishing the downstream PI3K/AKT/mTOR pathway in the presence of the anti-EGFR inhibitors, ultimately converting a TKI-sensitive tumor into a TKI-resistant tumor." (PMID 33123479, 2020). "It has been shown that H. pylori regulates several signaling pathways in gastric epithelial cells, including epidermal growth factor receptor (EGFR) activation, which is overexpressed in GC and involved in tumor cell motility, invasion and metastasis." (PMID 33198323, 2020). "Moreover, TZD drugs elicit tumor-suppressive effects to induce apoptosis and inhibit cell proliferation in various cancer cells by regulating apoptosis-associated proteins, such as cyclooxygenase-2 (COX-2), B-cell lymphoma 2 (Bcl-2), epidermal growth factor receptor (EGFR) and Fas ligand (FasL)." (PMID 33266062, 2020). "A transient benefit from treatment with anti-EGFR targeted therapies initially occurs due to bulk killing of drug-sensitive RAS/BRAF wt cells and consequent measurable tumor volume reduction." (PMID 32183295, 2020). "Palmitoylation is essential for the function of both oncogenes (e.g., HRAS, NRAS, and epidermal growth factor receptor [EGFR]) and tumour suppressors (e.g., SCRIB, melanocortin 1 receptor)." (PMID 32526973, 2020). "During the previous decades, numerous genetic variations have been described in NSCLC, including epidermal growth factor receptor (EGFR), KRAS and anaplastic lymphoma kinase (ALK), as the most commonly altered oncogenes acting as tumor driver genes." (PMID 33022831, 2020). "We believed that overexpressed EGFR provided greater targets for HSP90 inhibitors, therefore 17-AAG manifested a more significant effect on USP8 mutant tumor cells." (PMID 33537004, 2020). "To determine if hnRNP A3 showed nuclear colocalization with EGFR in NSCLC, we used immunofluorescence (IF) staining to examine the expression patterns of these proteins in the paired tumor and adjacent normal tissues of an overall stage 3 patient." (PMID 32321917, 2020). "Two studies showed that fedratinib in combination with erlotinib (EGFR tyrosine kinase inhibitor) decreased STAT3 activation and increased apoptosis in erlotinib-resistant NSCLC cells and inhibited tumor growth in in vivo murine models." (PMID 33521321, 2020). "Inherbin3, an antagonist of epidermal growth factor (EGF)-EGFR signaling, inhibits EGF-induced EGFR phosphorylation, cell growth and migration in human tumor cell lines and suppresses tumor growth in a tumor xenograft model." (PMID 32001707, 2020). "The study also found that tetrahydrocurcumin downregulated COX-2, EGFR, p-ERK1/2, and p-AKT in CaSki tumor tissue; it is likely that this downregulation is a part of the overall mechanism of angiogenesis inhibition and tumor-volume reduction." (PMID 32486019, 2020).